LINC02345 (long independently transcribed non-coding RNA 2345)
Gene: Long non-coding RNA gene on chromosome 15 (37,980,676 to 38,062,357, forward strand). Ensembl gene ENSG00000259225.
Diseases named in the same sentence as LINC02345 in open-access papers:
LINC02345 is named in the same sentence as 2 diseases in open-access papers, as found by Europe PMC text mining. Sharing a sentence is not in itself a finding about the gene and the disease. The quoted sentences say what the papers report.
clear cell renal cell carcinoma (1 paper, 2023). "Also, LINC02345 is a prognostic marker in clear cell renal cell carcinoma." (PMID 36724022, 2023).
cancer (1 paper, 2021). A tumor composed of atypical neoplastic, often pleomorphic cells that invade other tissues. "However, SRD5A3-AS1, U62317.3, and LINC02345 have not yet been reported in cancers." (PMID 34958632, 2021).